BTK (Bruton tyrosine kinase)
Diseases named in the same sentence as BTK in open-access papers (continued):
Sharing a sentence is not in itself a finding about the gene and the disease.
cancer (continued). "The expression of genes in NPC tissues and normal tissues was observed, and it was found that the expression of BTK, CD72, PTPN6, and VAV1 was different in cancer and normal tissues, and the expression was lower in both cancer and normal tissues." (PMID 35957889, 2022). "Using molecular knockdown and ibrutinib, we demonstrated that the inhibition of BTK signaling markedly reduces the subpopulation of CSCs and enhances the anticancer effects of conservative chemotherapy in ovarian and GBM cancer cells." (PMID 34577576, 2021). "Ibrutinib, which is already FDA approved for use in certain types of cancers, can be explored further as a potential therapeutic molecule, as well as further development of LFM-A13 or other BTK inhibitors." (PMID 34895246, 2021). "Because BTK is known to be expressed in both cancer cells and immune cells, we focused on defining the cell types within GBM tissue where BTK is expressed." (PMID 34645618, 2021). "In the present work, we explored the prospect of repositioning branebrutinib (BMS-986195), a highly selective inhibitor of Bruton’s tyrosine kinase (BTK), to resensitize P-gp-overexpressing multidrug-resistant cancer cells to chemotherapeutic agents." (PMID 34350184, 2021). "The fact that several cancers are related to constitutive BCR signaling, including BTK activity, has rendered BTK as an important therapeutic target including small-molecule inhibitors." (PMID 34349760, 2021). "We also used the Q-score method to represent the quantitative difference in BTK expression between treatment-naïve and CCRT-resistant cancer tissues." (PMID 33640903, 2021). "For this reason, as a future scope of research, we aim to study the mechanisms by which BTK inhibitors target AKR1C3 and AKR1B10 and modulate cell proliferation for potential applications in cancer treatment." (PMID 33322571, 2020). "Bruton's tyrosine kinase (BTK), a downstream of PI3Kγ, has been investigated as a target for cancer treatment." (PMID 33251232, 2020). "In conclusion, this study outlined the ability of the BTK inhibitors ibrutinib and acalabrutinib to prevent the AKR1C3-mediated reduction of daunorubicin, which contributed to their synergistic effect on cancer cells expressing AKR1C3." (PMID 33322571, 2020). "To this end, we synthesized previously reported BTK degraders DD-03-17132 and MT-80231 and compared them head-to-head with RC-1, RNC-1, and IRC-1 in their abilities to inhibit cancer cell growth." (PMID 32848159, 2020). "Recently, several studies showed that B lymphocytes support PDAC carcinogenesis and progression stimulating cancer cell proliferation, suppressing CD8+ cells through the Bruton tyrosine kinase (BTK) pathway." (PMID 30662458, 2018). "BMX, BMPR1B, BTK, and MDC1 belong to the COSMIC_mut gene set, and CSNK2A2 belongs to the COSMIC_other gene set, while ASH2L belongs to the non-cancer gene set." (PMID 19765316, 2009). "The covalent BTK inhibitor ibrutinib, a small-molecule inhibitor, has been found to be efficient against B cell cancers by inhibiting BCR signaling, thus suppressing the proliferation and survival of cancer cells." (PMID 40917692, 2025). "Numerous studies have shown that pyrazole derivatives possess good inhibitory activities against various targets in cancer cells, such as EGFR, VEGFR-2, CDK, BTK, and BRAF V600E, etc., which play an important role in anticancer drugs (details are provided below)." (PMID 37628906, 2023). "Our recent preclinical studies with the first-generation BTK/PI3K/BRD4 inhibitor SRX3262 in MCL demonstrated reduced phosphorylation of MYC at Ser62 and Thr58, which are critical mediators of MYC protein stability and degradation in cancer." (PMID 35743155, 2022).
cancer (continued). "Additionally, many other PROTACs have already been developed or are being developed based on IMiDs recruiting CRBN to target cancer-related proteins, including CDK6, MCL-1/BCL-2, BCL-xL, HDAC6, BTK, BRAF, FKBP12, PARP1, BCR-ABL, FAK, and PD-L1." (PMID 36140200, 2022). "In this study, through the analyze of the data from the Gene Expression Omnibus, the Cancer Genome Atlas and the Genotype-Tissue Expression, we found that the expression of KLRG1, BTK, CCR2 and SCML4 was significantly downregulated in LUAD tissues compared to normal controls." (PMID 34187403, 2021). "In radiation-tolerant OSCC cells, BTK may be involved in the EGFR/AKT/mTOR signaling pathway and increase the drug sensitivity of cancer cells after radiotherapy." (PMID 33640903, 2021). "The data provide support for a strategy to better mimic GBM tissue ex vivo by reconstituting more physiologically heterogeneous cell co-culture models that include BTK-positive/negative cancer and immune cell populations." (PMID 34645618, 2021). "Small molecule inhibitors targeting cellular oncoproteins and enzymes such as BCR-ABL, JAK2, Bruton tyrosine kinase (BTK), FLT3, BCL-2, IDHs, have fundamentally transformed the landscape of cancer therapy from cytotoxic chemotherapy to biomarker-driven precision therapy." (PMID 33879198, 2021). "First, we demonstrated that BTK was highly expressed in CCRT-resistant OSCC tissues and influenced clinical survival, as evidenced by IHC staining of the TSGH OSCC tissue array, compared with treatment-naïve cancer tissue." (PMID 33640903, 2021). "In this study, we explored whether RN486, another BTK inhibitor, was competent to surmount ABCB1-mediated MDR and promote relevant cancer chemotherapy." (PMID 32984343, 2020). "For instance, while MITF, SPDEF, CNOT7, BTK, PAF1, and PAX5 seem to be novel key regulators in the context of HPV-induced carcinogenesis, they are apparently already known to play essential roles in other cancer entities." (PMID 30918060, 2019). "Covalent cysteine binding drugs have gained renewed interest, since the Food and Drug Administration (FDA) awarded a “breakthrough drug” status to cysteine-directed covalent inhibitors that target Bruton’s tyrosine kinase (BTK) and a drug-resistant EGFR mutant in cancer." (PMID 29163463, 2017). "Additionally, PRO TACs (such as the DD04015 and the DD03171) were developed using a new class of noncovalent BTK inhibitors that effectively degrade the BTKs and slow cancer cell development." (PMID 39898116, 2025). "The appraisal of recent successes in the development of BTK inhibitors, despite the lack of entirely satisfying results, implies that continuous development of novel cancer-fighting strategies will bring us to a new generation of drugs and a better outcome for patients." (PMID 36903645, 2023). "BTK silencing significantly decreased the expression of the Janus kinase 2 (JAK2)/signal transducer and activator of transcription 3 (STAT3) and, in consequence, reduced cancer cell viability via the SRY-box transcription factor 2 (Sox-2) and BCL-XL genes and increased susceptibility to cisplatin." (PMID 36903645, 2023). "Similarly, cancer therapeutic effects of WA could also be observed in GC-sensitive MM1S cells, which lack BTK overexpression, through covalent targeting of alternative cell survival kinases expressed in MM1S." (PMID 33807411, 2021). "In this regard, we demonstrated that Bruton’s tyrosine kinase (BTK) inhibitors ibrutinib and acalabrutinib efficiently prevented daunorubicin (Dau) inactivation mediated by AKR1C3 in both its recombinant form as well as during its overexpression in cancer cells." (PMID 33322571, 2020).
cancer (continued). "Bruton's tyrosine kinase (BTK) is a non-receptor protein kinase that plays a crucial role in various biological processes, including immune system function and cancer development." (PMID 37848584, 2023). "Zanubrutinib, the most recently approved BTK inhibitor, has not yet been evaluated for repurposing for solid tumours, although its biochemical and pharmacokinetic properties suggest possible activity towards HER2-overexpressing cancers." (PMID 36913160, 2023). "For patients newly diagnosed with OSCC, BTK gene expression did not significantly influence the overall survival; however, it significantly influenced the overall survival in CCRT-resistant relapse cancer patients." (PMID 33640903, 2021).
infection (62 papers, 2013 to 2026). The state of being infected such as from the introduction of a foreign agent such as serum, vaccine, antigenic substance or organism. "Bruton's tyrosine kinase (BTK) inhibitors have revolutionized B-cell malignancy treatment but paradoxically increase infection susceptibility." (PMID 42192981, 2026). "Patients with CLL face an increased risk of infections due to the immunosuppressive nature of the disease and the effects of treatment, including BTK inhibitors and anti-CD20 monoclonal antibodies." (PMID 40647394, 2025). "Unfortunately, BTK inhibitor therapy amplifies the risk of invasive infections, including fungal pathogens, particularly in dissemination to the central nervous system (CNS)." (PMID 38713531, 2024). "It occurs in around one in 200,000 live births and is caused by mutations in the Bruton Tyrosine Kinase (BTK) gene leading to B lymphocyte deficiency and increased susceptibility to infection." (PMID 36644069, 2022). "Significant independent risk factors for infections were a higher Charlson Comorbidity Index, IgG deficiency, and 3rd + line treatment, as well as therapy with BTK inhibitors or chemotherapy in CLL." (PMID 35257229, 2022). "In the present multivariable analysis, patients on BTK inhibitor therapy had a significantly increased risk of infection." (PMID 35257229, 2022). "In the subgroup of CLL, patients treated with BTK inhibitors (HR 5.54 (95% CI 1.21–24.49; p = 0.027)) and chemotherapy (HR 5.54 (95% CI 1.21–24.49) p = 0.027) had a higher risk for severe infections." (PMID 35257229, 2022). "The immunological defects associated with BTK deficiency are likely only partially corrected by current approaches to treatment and prevention of infection, which differs little from Bruton’s original prescription of immunoglobulin replacement and antibiotics." (PMID 34164761, 2021). "Concerns about infectious events led several scientific groups to recommend more attention to the infection risk of patients treated with BTK inhibitors and other targeted molecules." (PMID 34209515, 2021). "On the other hand, targeting BTK with ibrutinib causes significant immunosuppression associated with an increased risk of infections indicating that BTK dependent innate immunity is severely impaired." (PMID 29167667, 2017). "Second-generation covalent BTK inhibitors mostly have higher target selectivity and less off-target toxicity, but they can still cause adverse reactions, such as headache, diarrhea, and infection." (PMID 39777345, 2024). "Patients with CLL on BTK inhibitor therapy are at risk of infections, which may in part be attributed to the biology of the disease itself and may also be partially caused by on- and off-target effects and drug-induced cytopenia." (PMID 37185435, 2023). "Because BTK inhibition in patients treated with ibrutinib does not generally result in immunoglobulin depletion, the increased risk for infection might be explained by other putative mechanisms associated with BTK." (PMID 36823687, 2023). "However, it is important to note that BTK inhibitors impair the innate immunity and increase susceptibility to infections." (PMID 35159041, 2022). "Moreover, we demonstrated that BTK-deficient mice are unable to control infection with this fungus, which is normally kept in check by monocytes/macrophages and neutrophils." (PMID 32503877, 2020). "Thus, targeting BTK with ibrutinib in a population already characterized by an immune dysregulation (e.g. CLL) will most likely result in an increased risk of infection." (PMID 30700842, 2019). "Although combining two complementary immunosuppressive mechanisms may carry increased risk of serious infection, a reversible BTK inhibitor such as BMS-986142 may mitigate this risk as precise titration to ensure optimal efficacy could avoid unnecessary and prolonged immunosuppression." (PMID 28742141, 2017).
infection (continued). "HeLa cells were transfected with either wild-type (WT)-BTK or the mutants for 24 h, followed by infection with VACV-WR at 3 pfu/cell." (PMID 40833106, 2025). "Rates of infection are highest in the first 12 months from commencing targeted BTK inhibitor therapy and are even more prevalent in relapsed or refractory patients." (PMID 40766049, 2025). "Collectively, these data indicate that BTK is dispensable for neutrophil recruitment and survival at the site of infection and for the production of proinflammatory mediators in the Aspergillus-infected lungs." (PMID 38696257, 2024). "Infections are most common within the first year of BTK inhibitor therapy and are more common in patients being treated in the relapsed setting." (PMID 37185435, 2023). "The incidence of infection (of any grade) is observed in > 50% of patients receiving BTK inhibitor treatment." (PMID 37845755, 2023). "Infections were common in patients treated with BTK inhibitors because patients with B-cell malignancy are immunocompromised and at a highly increased risk of infections despite receiving effective therapy." (PMID 37845755, 2023). "Rates of grade ≥3 infections occur at a similar rate among the BTK inhibitors (20–30%), with pneumonia being the most common grade ≥3 infection reported." (PMID 37185435, 2023). "Drug–drug and drug–food interactions as well as the presence of infection and vaccination in the patients need to be considered before starting them on BTK inhibitor therapy." (PMID 37845755, 2023). "Infection, cardiovascular toxicities, and haemorrhage were the most common AEs mentioned in the instruction manuals for BTK inhibitors." (PMID 36438789, 2022). "The increased infection rate can be attributed to the impairment of innate and adaptive immunity by the BTKi via inhibition of BTK (on-target effect) and ITK (off-target effect) signalling pathways." (PMID 36138486, 2022). "BTK inhibitor treatment should be withheld from patients demonstrating grade ≥3 neutropenia and infection or fever until resolution to baseline or grade 1; following this, the treatment can be restarted at a reduced dose." (PMID 35159041, 2022). "On the other hand, overactivation of BTK can be detrimental by driving infection-induced hyperinflammation." (PMID 36183125, 2022). "BTK has diverse functions in the infection of different bacteria at different stages due to the various immune responses." (PMID 36183125, 2022). "At the time of infection 51 patients (27.1%) were treated with Bruton tyrosine kinase inhibitor (BTKi), 46 (24.5%) with anti-CD20 antibodies while 37 patients (19.7%) received venetoclax." (PMID 35158826, 2022). "Myeloid cell lineages contribute to inflammation and infection, making BTK an interesting candidate for therapeutic intervention in a variety of disease settings." (PMID 33818636, 2021). "We did not detect significant differences in host cell viability or bacterial intracellular survival for these compounds, suggesting a BTK-independent mechanism of action due to an off-target effect of Ibrutinib in our model of infection." (PMID 30890742, 2019). "fumigatus infection, and more severe lung tissue damage and fungal burden were assessed by histology, indicating a contribution of BTK to the innate immune control ofAspergillus infection." (PMID 31372213, 2019). "Non-covalent inhibitors (Pirtobrutinib) and emerging BTK degraders offer more selective inhibition, preserving T-cell function and potentially mitigating infection risk, though their long-term immunological impact requires further study." (PMID 42192981, 2026). "Finally, as targeted agents such as BTK and BCL-2 inhibitors continue to reshape treatment, we need a better understanding of how they influence infection risk and immune recovery over time." (PMID 40647394, 2025). "We next leveraged a neutrophil swarming assay to determine how coordinated chemotaxis to the site of infection and containment of fungal growth may be affected by BTK inhibition." (PMID 38713531, 2024).